BACE1 (beta-secretase 1)
Diseases named in the same sentence as BACE1 in open-access papers (continued):
Sharing a sentence is not in itself a finding about the gene and the disease.
infection (21 papers, 2007 to 2023). The state of being infected such as from the introduction of a foreign agent such as serum, vaccine, antigenic substance or organism. "BACE1 expression after infection was also increased in COs, but the expression levels were lower than fCBOs." (PMID 36697403, 2023). "The timing for drug treatment of CHME3 4 × 4 or 293T cells with γ-secretase inhibitor or BACE1 inhibitor was incorrectly given as ‘1 day prior to infection or transfection’ and should have stated ‘4 or 6 h post transfection or infection, respectively’." (PMID 29872052, 2018). "After infection, APP and BACE1 expression levels of fCBO were increased whereas γ-secretase complex proteins including PSEN1/2 levels were not." (PMID 36697403, 2023). "PRR was knocked down by infection of MC3T3 cells (an osteoblastic cell line that expresses PRR, APP and BACE1) with shRNA-PRR lentivirus." (PMID 31108937, 2019). "Inhibition of the common shedding proteases BACE1 and BACE2, which are expressed in A549 cells, with the drug C3 did not alter GFP expression, ruling out an involvement of both proteases in SARS‐CoV‐2 spread in this infection model." (PMID 35527514, 2022). "The transcripts of APP, ADAM10, BACE1, and subunits of the γ-secretase complex (PSEN1, PSEN2 APH1A and NCSTN) were significantly upregulated (p < 0.05) in at least one of the 4 investigated timepoints post-infection." (PMID 30786875, 2019). "Additionally, the increase in BACE1 protein expression observed with these studies does not seem transient; as time of infection progresses, BACE1 protein levels continued to increase throughout the 72 h of infection." (PMID 30786875, 2019).
tumor (17 papers, 2016 to 2025). "We found that loss of BACE1 expression markedly impaired LBM tumor growth in the brain, which resulted in a considerable extension in survival." (PMID 40601773, 2025). "We also observed an increased expression of FOXO1 with BACE1 inhibition, associated with reduced cell proliferation and reduced tumor volume." (PMID 38201438, 2023). "In another hand over expression of BACE1 in poorly differentiated tumours were significantly associated with moderate or well differentiated samples." (PMID 36087249, 2022). "As well as PINT, over expression of BACE1 is significantly associated with distant metastasis in CRC tumours." (PMID 36087249, 2022). "Also, BACE1 over expression was significantly associated with tumour site (p < 0.009), metastasis (p < 0.017) and histological differentiation (p < 0.028) and staging (p < 0.017)." (PMID 36087249, 2022). "We allowed tumors to form for seven days before randomly assigning BACE1-activated, or control, tumor bearing mice to vehicle or MK-8931 treatment groups." (PMID 40601773, 2025). "Plasmin, proprotein convertase PC5A, cathepsin E, MBP, presenilin/gamma-secretase, beta-secretase 1/BACE1, metalloproteinases and neuropsin have been identified as L1-cleaving proteases in neural and tumor cells." (PMID 38672483, 2024). "A recent intriguing study identified the β-site amyloid precursor protein cleaving enzyme 1 (BACE1) as playing a role in preventing tumor phagocytosis." (PMID 39194679, 2024). "We also observed reduced tumor growth with BACE1 inhibitor treatment in the TRAMP-C1 allografts in syngeneic mice, signifying the role of BACE1 in the growth of PCa." (PMID 38201438, 2023). "The effect of the pharmacologic inhibition of BACE1 on tumor growth was investigated using an in vivo syngeneic mouse PCa model." (PMID 38201438, 2023). "The in vitro and in vivo effects were only studied with MK-8931 treatment, which inhibits BACE1 activity, but the study should also be validated with BACE1 knockdown/knockout and overexpressing cell lines and tumor models." (PMID 38201438, 2023). "In our study, BACE1 expression levels were reduced in tumoural tissues with metastasis, while in another study on cancerous liver patients, BACE levels were increased." (PMID 36087249, 2022). "We found the expression of BACE1 was significantly higher in the tumoural metastasis tissues and adjacent normal tissues than control tissues." (PMID 36087249, 2022). "Having demonstrated that NETosis can be modulated by the β-secretases activity on APP, they wondered how this process influences tumor growth and observed that inhibiting BACE1/2 in skin tumor bearing mice results in a strong reduction of tumor volume." (PMID 33926496, 2021). "On the other hand, BACE1 inhibition promotes a switch from pro-tumoral macrophages (pTAM) to tumor suppressive macrophages (sTAM)." (PMID 33926496, 2021). "The majority of tumors (80%) had increased IRA mRNA, and changes in tumor IRA expression were positively correlated with BACE1 expression, suggesting that these tumors efficiently cleave IRA and produce IRsol." (PMID 29610518, 2018). "This suggests that a patient population otherwise not being considered for EGFR-targeting tyrosine kinase inhibitors in a front-line setting due to lack of mutations detected by sequencing, may benefit from such a therapy if BACE1 is present in their tumor." (PMID 40601773, 2025). "Given the link between self-renewal capacity in vitro and tumor initiating capacity in vivo, we first assessed whether BACE1 expression was important for LBM tumor growth in the brain." (PMID 40601773, 2025). "Furthermore, it was demonstrated that BACE-1 is expressed in tumor-promoting macrophages and the administration of MK-8931 along with IR was able to suppress malignant GBM growth in vivo." (PMID 39194679, 2024). "There are only a few studies suggesting the molecular role of BACE1 in tumor progression." (PMID 38201438, 2023).
tumor (continued). "However, the expression of BACE1 was relatively higher in human PCa tumor tissue compared to that in the NSVs or NP." (PMID 38201438, 2023). "Interestingly, BACE1 inhibition, with a selective chemical inhibitor MK-8931, reprogrammed the tumor-promoting macrophages into tumor-suppressive macrophages that promoted phagocytosis of glioma cells." (PMID 38201438, 2023). "However, contradictory studies have shown that both Aβ and BACE1 inhibitors can inhibit angiogenesis in tumor models." (PMID 35119166, 2022). "It is interesting that BACE1 over expression was significantly observed in transverse resected tumours where it could be compared with PINT with down regulation." (PMID 36087249, 2022). "BACE1 inhibitors have previously been shown to inhibit angiogenesis and tumour growth." (PMID 32029735, 2020). "Notably, BACE1 expression in the primary tumor was maintained in the BM." (PMID 40601773, 2025). "Although, Aβ produced by BACE1 could play a key role in the complex tumor microenvironment." (PMID 38201438, 2023). "Collectively, these data confirm that BACE1 plays an essential role in LBM cell and tumor growth and provide evidence that targeting BACE1 with the BBB permeable MK-8931 represents a clinically relevant approach to treat BM." (PMID 40601773, 2025). "We discovered that PINT and BACE1 expression levels were decreased and increased respectively in CRC tumour samples compared with ADJ normal and healthy tissues." (PMID 36087249, 2022). "Over expression of BACE1 developed significant relations with TNM staging of disease (p value: 0.01), tumour histological differentiation (p value: 0.02), growing tumour location (p value: 0.009) and far apart metastasis (p value: 0.01)." (PMID 36087249, 2022). "Increasing the level of BACE1 reduces STGAL1 enzyme expression, thus eliminating the important role of this enzyme in reducing tumour metastasis." (PMID 36087249, 2022). "In particular, the BACE1/2 dependent maturation of amyloidogenic proteins such as APP or PMEL, has been shown to affect TME cells behavior and to act both in paracrine and autocrine way driving tumor proliferation and progression." (PMID 33926496, 2021).
neurological disease (10 papers, 2012 to 2025). "Several key enzymes, such as acetylcholinesterase (AChE), beta-secretase (BACE1), tau kinases, monoamine oxidase, caspases, and cyclooxygenase-2, reportedly play significant roles in the development of neurological disorders." (PMID 40429850, 2025). "There are several enzymes, such as sphingomyelinases, acetylcholinesterase, monoamine oxidase, beta-secretase (BACE1), Tau kinases, caspases, and cyclooxygenase-2 (COX-2), which are directly or indirectly linked with the progression of neurological disorders." (PMID 40429850, 2025). "Three main biomarkers, Paraoxonase-1 (PON-1) in CVD, Matrix Metalloproteases (MMPs) in both CVD and neurological diseases, and Beta-Secretase-1 (BACE-1) in AD have been proposed as indicator of sex-specific disease phenotypes." (PMID 38560614, 2024). "BACE1 protein levels and activity in microglia were shown to be increased in several neurological diseases." (PMID 37552127, 2023). "Currently, a handful of aptamers against β-secretase BACE1, amyloid fibril constituent Aβ and PrP have been established for neurological disorders and are still at pre-clinical stage." (PMID 23130020, 2012). "BACE1 is a transmembrane protease responsible for the β-site cleavage of the amyloid precursor protein to produce Aβ, and Aβ is an important component of plaques in neurological disease and drusen deposits in AMD." (PMID 33670685, 2021).
metabolic disorders (8 papers, 2018 to 2025). "Inflammation is closely associated with metabolic disease, and increases in BACE1 expression in response to inflammation have been attributed to transcriptional regulation." (PMID 35119166, 2022). "Restoring the content of S1P in AD mice can regulate metabolic disorders, improve the functions of body cells, alleviate neuroinflammation caused by abnormal content in brain tissue, change the proteolytic activity of β-secrease BACE1, control the production of Aβ protein, and alleviate AD." (PMID 39997718, 2025). "Additionally, repurposing BACE1 inhibitors currently undergoing clinical trials for AD for moderation of peripheral Aβ levels could be a novel therapy for vascular dysfunction induced by metabolic disease." (PMID 32407295, 2020).
cardiovascular disease (3 papers, 2007 to 2022). "Together, this presents an important physiological role for BACE1 within the cardiovascular system and as an important enzyme in cardiovascular disease." (PMID 35119166, 2022). "Given the more recently described roles of BACE1 in metabolism and cardiovascular disease, and the lack of knowledge surrounding BACE1 substrates, this computational analysis could present a first step into deciphering the roles of BACE1 in health, disease, and importantly in AD." (PMID 35562959, 2022).
brain disease (2 papers, 2017 to 2024). "Diminished miR-186-3p allows increased BACE1 mRNA translation and cleavage of amyloid peptides that increase the risk for brain disease." (PMID 29127316, 2017).
retinopathies (2 papers, 2017 to 2018). "The BACE1-null mice present neuronal phenotypes including synaptic dysfunction, retinopathy, epileptic seizures, hypomyelination, etc., that appear to be related to the abolished cleavage of BACE1 substrates." (PMID 29881722, 2018). "BACE1 was initially suggested to mediate these retinopathies in a report that BACE1-null mice were found to develop retinal thinning, apoptosis, reduced retinal vascular density, and an increase in age pigmentation and lipofuscin." (PMID 28469554, 2017). "While retinopathy is closely monitored in BACE1 inhibitor clinical trials, recent studies have shown that it is likely due to cross-inhibition of cathepsin D by BACE1 inhibitors." (PMID 28469554, 2017).
adenocarcinoma (1 paper, 2023). A common cancer characterized by the presence of malignant glandular cells. "BACE1 expression was observed in human PCa tissue samples, patient-derived xenografts (PDX), human PCa xenograft tissue in nude mice, and transgenic adenocarcinoma of the mouse prostate (TRAMP) tissues by immunohistochemistry (IHC) analysis." (PMID 38201438, 2023).
myopathy (1 paper, 2016). A disease of the muscle in which the muscle fibers do not function properly. "The Akt impairment detected in GNE myopathy myoblasts is likely mediated by Aβ since it was prevented by a β-secretase BACE1 inhibitor, which inhibits cellular Aβ generation." (PMID 26968811, 2016).
BACE1 also shares sentences with these, for which no sentence is quoted: Chagas disease (5 papers); parasitemia (5); familial Alzheimer disease (4); Brain atrophy (3); psychiatric disorder (3); amyloid cerebral angiopathy (2); CADASIL (2); cardiac disease (2); cognitive disorder (2); frontotemporal dementia (2); Lewy Body disease (2); lipid metabolism disorder (2); Niemann-Pick type C disease (2); Parkinson's (2); preeclampsia (2); skin cancer (2); adenoma (1); Allergy (1); arteriolosclerosis (1); Ataxia (1); Autosomal dominant cerebral arteriopathy with subcortical infarcts and leukoencephalopathy (1); behavioral disorder (1); breast ductal carcinoma (1); cardiomyopathy (1); cervical carcinoma (1); cognitive (1); colorectal neoplasm (1); coronary artery disease (1); coronary atherosclerosis (1); COVID-19 (1).
A further 39 diseases each share a sentence with BACE1 in 1 paper.